RB1 (RB transcriptional corepressor 1)
Diseases named in the same sentence as RB1 in open-access papers (continued):
Sharing a sentence is not in itself a finding about the gene and the disease.
tumor (continued). "Although homologous recombination (HR) deficiency and retinoblastoma gene (RB1) expression have been implicated in prognosis, their combined role in shaping tumor biology and survival outcomes is not well defined." (PMID 40796942, 2025). "RB1 is present in the primary tumour and LNM and then disappears in DM." (PMID 40729029, 2025). "Additionally, WGS analysis of CRPC metastases has shown significant intra-patient molecular heterogeneity, with RB1 expression often varying within the same tumor." (PMID 39796175, 2025). "This is likely driven by the high frequency of RB1 mutations, elevated TGF-β expression, and increased immunosuppressive gene expression, all of which contribute to a profoundly suppressive tumor microenvironment that ablates T cell anti-tumor activity." (PMID 41567195, 2025). "Additionally, RB1, a pivotal tumor suppressor and the first of its kind identified, was detected across multiple analysis methods, although not by EPIC." (PMID 39859246, 2025). "Indeed, we found that XPO1 can exert a tumor‐promoting function by reducing the nuclear localization of RB1." (PMID 39888288, 2025). "Cell cycle regulation is critical in tumor development, and as the RB1 gene is a key tumor suppressor involved in cell cycle regulation, its inactivation may contribute to uncontrolled cell proliferation." (PMID 40723400, 2025). "In the case that no RB1 mutations are detected in the tumor, a test for RB1 promoter hypermethylation can be performed to examine epigenetic silencing." (PMID 41009976, 2025). "Moreover, mutual interactions between different tumor microenvironment clusters and epithelial cells are more prolific in adjacent and RB1‐CN‐wildtype samples than in RB1‐deleted samples." (PMID 40904703, 2025). "This is particularly significant since RB1, a tumour suppressor, cannot be targeted directly." (PMID 40775769, 2025). "The loss of RB1 function and high levels of CCNE1 expression resulted in a decrease in ESR1 and PRG expression levels and hormone-dependent reactivity, which demonstrates that RB1 status is related to the growth and proliferation of hormone-dependent tumor cells." (PMID 39544302, 2024). "In contrast, RB1 loss and other oncogenic alterations that enhance OXPHOS (see previous subsection) promote both primary tumor growth and metastasis and therefore may be selected for during clonal evolution." (PMID 37322261, 2024).
tumor (continued). "Interestingly, we found the most prominent changes in gut microbiota diversity and composition from fecal samples of animals with end point TRAMP-C2 tumours and tumours with combined Pten and Rb1 deletions." (PMID 38654015, 2024). "RB1 was deleted or downregulation was seen in 17% of tumours." (PMID 38612869, 2024). "RB1 exerts its tumor suppressor function through three primary mechanisms." (PMID 39664374, 2024). "Our data thus suggest a double hit inactivation of the RB1 gene in the p16‐high class A tumours." (PMID 36453028, 2024). "Finally, profile A tumours, including those with RB1 deletion, were observed in the different histotypes." (PMID 36453028, 2024). "Interestingly, tumours with combined Pten and Rb1 deletion and TRAMP-C2 tumours caused greater changes in the gut microbiota of recipient animals compared to tumours characterized by the loss of Pten alone." (PMID 38654015, 2024). "RB1 tumor expression was classified as either retained or lost in 6,564 samples, with 872 samples excluded that had either subclonal loss (n = 66), cytoplasmic (n = 17), or uninterpretable results (n = 789) due to either sample drop out or the absence of an internal positive control." (PMID 38837893, 2024). "Nevertheless, seven tumours were observed with defects or very low expression of both RB1 and CDKN2A, showing that the coexistence of both defects in MPM_36 cells might not result from a culture artefact." (PMID 36453028, 2024). "Just as in the case of previously detailed genes, RB1 mutations also have tumor-promoting effects and disrupt normal cell biology in many cancers, including GBM." (PMID 39062807, 2024). "Furthermore, we immortalized cells of a RB1 mutated, MYCN amplified and trefoil factor family peptid 1 (TFF1) positive RB tumor and RB derived non-tumor stromal tissue." (PMID 39695086, 2024). "RB1 staining of tumor tissue by IHC is a relatively low-cost pathology-based assay that could be used in prospective studies to test whether RB1 expression is predictive of responses to PARP inhibitors, either alone or in combination with approved HRD tests." (PMID 38837893, 2024). "Through the study of the RB1 tumor suppressor, Dr. Knudson suggested that individuals inherit one defective copy of a tumor suppressor gene (the “first hit”) and acquire a second mutation in the other copy of the gene (the “second hit”) over time, leading to the development of cancer." (PMID 38672640, 2024). "However, the complex interplay between RB1 and either lineage-dependent or independent cellular pathways presents challenges in fully elucidating its tumor-suppressive role across different cancer types." (PMID 38672640, 2024).
tumor (continued). "The retinoblastoma 1 (Rb1) gene is deleted in 8% and mutated in 2% of HGSOCs, while amplification of the cyclin E1 gene, CCNE1, one of the most common focal copy number change events in HGSOC, occurs in 20% of tumours." (PMID 38785992, 2024). "While changes in the cell cycle regulators, including the amplification of cyclin D, activation of CDK, and loss of p21CIP1 or p27KIP1, may contribute to tumor adaptation to CDK4/6 inhibition, the main resistance is mediated by RB1 inactivation." (PMID 38927958, 2024). "Most tumours with previously identified RB1 defects were associated with very high CDKN2A transcript levels as expected, which were also observed in some tumours with very low RB1 transcript levels." (PMID 36453028, 2024). "Significant discriminative power in distinguishing tumor from normal tissues as well as molecular subtypes (RB1-mut vs -wt) may suggest NFYC-AS1 as a potential cancer biomarker." (PMID 38467619, 2024). "The lesser loss of microbiota alpha diversity in Pten−/−; Rb1+/+ compared to the TRAMP-C2 and Pten−/−; Rb1−/− mouse models suggests that genetic alterations within incipient tumours cells could contribute to cancer-gut microbiota interaction." (PMID 38654015, 2024). "However, a recent study reported RB1 deletions (possibly mostly monoallelic) in 26% of 118 MPM samples including in one‐third of tumours with CDKN2A deletions." (PMID 36453028, 2024). "Our findings suggest that targeting the AHR could hold therapeutic potential in ccRCC; the activation of this receptor, despite the constitutive HIF1A triggering, is shown to potentiate the tumour suppressor behaviour of both the AR and RB1." (PMID 39336758, 2024). "RB1, a tumour suppressor, plays a crucial role in regulating the G1/S transition of the cell cycle." (PMID 39336758, 2024). "Furthermore, we demonstrated the reason for the inability to produce IL-8 in tumour cells, although KDM5B was present in tumour cells, which was attributed to competitive binding by a compromised tumour suppressor gene, RB1, in tumour cells." (PMID 38862740, 2024). "Regarding RB1, 11 tumors and 8 non-tumor tissue samples presented methylation of the gene." (PMID 38716944, 2024). "The primary stromal cells did not carry the RB1 mutation present in the primary RB tumor cells, indicating their non-tumor identity." (PMID 37835522, 2023). "Another tumor suppressor gene frequently inactivated in OS is RB1, located at chromosome 13q14.2." (PMID 37511127, 2023). "In addition, a well-known tumor-suppressing retinoblastoma transcriptional corepressor 1 (RB1) was featured as a sensitivity-ensuring marker in several comparisons across the cell lines." (PMID 37242727, 2023).
tumor (continued). "The correlation is attributed to the effect of the viral protein E7 that is able to inhibit tumour suppressors, particularly Rb1 protein, which could result in an increased p16 level." (PMID 37185737, 2023). "Indeed, it was observed that Rb1 depletion in cone precursor cells derived from foetal retinal tissue and transplantation into orthotopic xenografts generates tumours suggesting that cone precursor cells are the cell of origin." (PMID 36177499, 2023). "However, in tumor cells with irreversibly lost RB1 function, the involvement of p107 or p130 in cell cycle regulation becomes prominent." (PMID 37182173, 2023). "Moreover, retinoblastoma 1 (RB1), the downstream target of CDK4/6, was associated with immunological features of tumor tissues." (PMID 37326143, 2023). "RB1 negatively regulates cell cycle progression and functions as a tumor suppressor gene in HCC." (PMID 37528384, 2023). "RB1 is reported to mediatethe cell cycle, adhesion and the tumor microenvironment." (PMID 37414817, 2023). "The inactivation of RB1 leads to the activation of E2F1, causing tumor cell proliferation." (PMID 37781033, 2023). "Furthermore, TFE3, TFDP1, NFYB, and RB1, associated with the cell cycle and apoptosis, were inferred in FSTL1+ tumor cells." (PMID 37430270, 2023). "Moreover, the mRNA expression levels of five PR and PD biopsy tumor samples were detected, and it was found that RB1 and downstream genes of PD biopsy tumor samples showed low expression." (PMID 37781033, 2023). "The retinoblastoma gene (Rb1), which codes for pRB, is the first tumor suppressor gene identified." (PMID 38132337, 2023).
tumor (continued). "Furthermore, an analysis of genes impacted by somatic copy number alterations unveiled a heightened occurrence of deletions in tumor suppressor genes, such as RB1, PTEN, and MAP3K7, among different LGG patients (all p < 0.05)." (PMID 37660060, 2023). "Therefore, active RB1 in abundance prevented the RB1+/+ tumor cells from developing the IFN-β-induced cell cycle alterations despite IFN-β signaling." (PMID 37182173, 2023). "Conversely, including HMT expression when predicting NNMT expression abrogates the negative relationship between NNMT expression and RB1 mutation status in tumours." (PMID 37883365, 2023). "Other genes, such as RB1, typically have anti-tumor action by arresting the cell in G-phases." (PMID 37509254, 2023). "Studies done in the early 2010s showed that these tumours formed in the retina, lacked RB1 mutations and instead showed amplification of MYCN gene." (PMID 37667345, 2023). "Most of PTEN and RB1 mutations found in our cohort are variants with uncertain significance and do not correlate with tumor progression." (PMID 35347810, 2022). "It is also known that several chromatin regulators are misregulated in RB and play a relevant role in tumor transformation following RB1 inactivation, including DNA methyltransferase (DNMT), Ubiquitin-like with PHD and ring finger domains 1 (UHRF1), and B lymphoma Mo-MLV insertion region 1 (BMI1)." (PMID 35432447, 2022). "Notably, HT72, HT77, and HT87 acquired a deletion of RB1 in one allele during the PDX serial passaging, which was not seen in the respective P0 sample, whereas HT96 maintained the RB1 deletion found in the original tumor." (PMID 36612255, 2022). "Importantly, the knockdown of RB1 remarkably rescued the tumor growth inhibited by the BECN1 depletion." (PMID 36230664, 2022). "Next, we observed upregulation in two tumor-suppressor genes: aminoacylase 1 and RB1." (PMID 36014345, 2022). "Transformed tumors maintain the EGFR mutation, in addition to RB1 loss, suggesting direct evolution from the original tumor rather than a distinct primary cancer." (PMID 35954436, 2022). "RB1, as a tumour suppressor, plays important role in cell cycle and metastasis in many cancers." (PMID 35969010, 2022). "Furthermore, in TP OPC and NFO, E2F7, which is found to be amplified in some tumours and controls the cell cycle by binding to RB1, is the downregulated eminent TF regulator." (PMID 34976314, 2022).